CD4 (CD4 molecule)
Diseases named in the same sentence as CD4 in open-access papers (continued):
Sharing a sentence is not in itself a finding about the gene and the disease.
tumor (continued). "Tumor inhibition associated immune cells, including CD8 T cells, CD4 memory activated T cells, and follicular helper T cells, were more abundant in HPV+ HNSC." (PMID 34530752, 2021). "For this reason, the prognostic value of the decreased tumor infiltrating CD4+ T cells observed after DICB is unclear, even though it reached significance when compared to control." (PMID 33772035, 2021). "In this study, we reported on the capacity of the introduced CD8α co-receptor to successfully redirect non-tumor reactive CD4+ TEG011 cells in vivo and in vitro against tumor targets that express HLA-A*24:02 molecules." (PMID 34759930, 2021). "CD4+ Th1 cells have been shown to prevent tumor growth, while CD4+ Th2 and CD4+ forkhead box P3+ lymphocytes (Tregs) are considered to promote tumor growth." (PMID 34228637, 2021). "Infiltration of both activated CD4+CD69+ T cells and regulatory Foxp3+CD4+ T cells into HNSCC tumor tissue contribute to prognosis." (PMID 33732250, 2021). "Second, which antigen-presenting cells are responsible for activating tumour-specific CD4+ T cells in the tumour microenvironment ?" (PMID 32457487, 2021). "As expected, in non-tumor bearing mice, proportions of CD4+ and CD8+ T-cells were significantly lower in lymph nodes and spleens of Pik3cg−/− mice compared to WT mice." (PMID 33668795, 2021). "Programmed cell death protein 1 (PD-1) and cytotoxic T lymphocyte-associated antigen 4 (CTLA-4) are co-inhibitory ICPs; they are expressed on activated tumor-specific CD4+ cells and CD8+ T-lymphocytes, and inhibit the progression of the immune reaction." (PMID 33783613, 2021). "Analysis of ID8 s.c. tumors immune profile revealed that TAX2 treatment not only increases the number of infiltrating CD4+, but also stimulates deeper T-cell infiltration within the whole tumor sections." (PMID 34638503, 2021). "As a subtype of CD4+ T cells, Tregs suppress the antitumor immune response and enhance the immune escape of tumor cells." (PMID 34249711, 2021). "GITR is also a widely used target that can activate the NF‐κB pathway via TNF receptor‐associated factors (TRAFs) and is highly expressed in tumor‐infiltrating CD8+ T cells and CD4+ T cells." (PMID 34658167, 2021). "There was a visible difference in the DNA methylation pattern in tumor infiltrating CD4+ T cells compared to blood and the corresponding RNA expression values reflected the effect of DNA methylation pattern." (PMID 34012510, 2021). "In a mouse model carrying the 4T1 breast cancer cell line, UBR5 depletion caused increased CD4+ T cells and CD8+ T cell levels in the spleen and decreased Treg and increased mature DCs in the tumor-draining lymph nodes, therefore inhibiting tumor growth." (PMID 33466790, 2021). "KV heterologous treatment significantly increased Th1 CD4+ T cells (% and numbers) in the tumor, while other T-helper subtypes (Th2, Th17, Tregs) were reduced in frequencies, but not in absolute numbers." (PMID 34885215, 2021). "Potent T cell responses and tumor growth suppression was detected when both, CD4 and CD8 T cell epitopes were expressed." (PMID 34209393, 2021). "The tumor infiltrating lymphocytes (TILs) isolated from the tumors were stained with CD4, CD25 and Foxp3 antibodies, and the stained cells were analyzed by flow cytometry." (PMID 34183739, 2021). "Immunohistochemistry was used to analyze tumor cell proliferation index and CD4+ T cells infiltration." (PMID 34485300, 2021). "CD4+ T subtype-mediated cytotoxicity, which is essential for virus control and anti-tumor immunity, has attracted increasing attention in recent years." (PMID 33435880, 2021). "Further analysis of the T cells subsets pointed specifically to CD4+ T cells effecting the tumour immune response." (PMID 34141724, 2021). "CD8+ cytotoxic T lymphocytes (CTLs) and CD4+ T helper (Th) cells are paramount immune cells for tumor cell elimination." (PMID 35111169, 2021).
tumor (continued). "After euthanasia, tumor-infiltrating lymphocytes were obtained and counted by flow cytometry for the ratio and number of CD4, CD8 T cells." (PMID 34447697, 2021). "VEGF recruits CD4+ Foxp3+ Tregs to the tumor microenvironment by interacting with neuropilin 1 on their cell surface." (PMID 33746989, 2021). "Recent research has underscored the significance of CD4+ TH cells as a component of anti-tumor immune response." (PMID 34012451, 2021). "It is somehow puzzling that cancer cells also produce CXCL9 and CXCL10 and that this correlates with a better prognosis, in part due to the induction of anti-tumor CD4+ and CD8+ T cells." (PMID 34944943, 2021). "Given the importance of T cells in the tumor microenvironment, we tested cytokine secretion in tumor infiltrating CD4+ T cells and CD8+ T cells." (PMID 34522232, 2021). "Similar to previous results of lexatumumab, MD5‐1‐treated tumor lysates had high CD4 and CD8 expression as compared to IgG1‐treated tumors." (PMID 33587338, 2021). "Previously, we showed the importance of reducing Tregs in the duodenum in NoV protective immunity, though simvastatin has been shown to increase FoxP3 expression in murine CD4 T cells in vitro and in tumor cells in mice." (PMID 34357979, 2021). "CD4+ T cells are, surprisingly, much more effective at controlling tumor growth within this model than CD8+ T cells." (PMID 34283809, 2021). "Although host antigens that elicit immune responses of transferred allogeneic CD4+ T cells can induce anti-tumor activity, only a small fraction of these CD4+ T cells are reactive against the host antigens." (PMID 34625113, 2021). "Th1-polarized CD4 + T cells are less frequent at the tumor site compared to Th2-polarized CD4+ T cells." (PMID 34805152, 2021). "TfR1 expression was remarkably associated with most gene markers of different immune cells, such as CD4+ T cells, CD8+ T cells, B cells, monocytes, tumor-associated macrophages (TAMs), neutrophils, M1 and M2 macrophages, dendritic cells and NK cells." (PMID 34518441, 2021). "Blocking antibodies against these checkpoints resulted in increased proliferation of CD8+ and CD4+ tumor infiltrating lymphocytes and cytokine production in response to stimulation." (PMID 33981303, 2021). "Everolimus plus letrozole increased the ratio of peripheral Tregs to CD4+ T cells and tumor PD-L1 expression, and decreased Ki67 index and tumor-infiltrating Tregs, and patients with a greater increase of tumor-specific CTLs showed more sensitive to NET." (PMID 34315439, 2021). "There was a large degree of tumor immune cell infiltration, including M0 macrophages, M2 macrophages, activated mast cells, neutrophils, and resting memory CD4 T cells, in patients with GBM and high PTPRN expression." (PMID 34976783, 2021). "Quantifying these expression differences for tumor cells relative to reactive CD4+ T cells revealed fold-changes of 0.26 for CD7, 1.40 for CD30, 3.20 for CD25, and 5.73 for Ki-67." (PMID 34795254, 2021). "In contrast, there was a significant increase in the population percentage of CD8+ T (CD3+CD8+) cells, and a significant reduction in the population percentage of Treg cells (CD4+FoxP3+) within the tumor when the mice were treated with PLGA-FAKi (P < 0.05)." (PMID 34112200, 2021). "Expression of activation markers and proteins involved in metabolic pathways together with the absence of early memory markers were nonetheless in agreement with the chronic stimulation of exhausted CD4 TILs at the tumor site." (PMID 33332284, 2021). "Overall, these results show that anti-tumor efficacy seen in vIL-2 treatment is associated with a modest frequency of CD8+ and CD4+ T cells and with a high expression of MHC-II positive infiltrating cells in the tumor microenvironment." (PMID 34084172, 2021). "Many of the anti-tumour CD4+ T cell responses described in the early days of cancer immunotherapy were specific for highly immunogenic self-derived antigens." (PMID 32457487, 2021).
tumor (continued). "PD-1/PD-L1 blockade indirectly offers improved NK cell survival and function by preventing the expansion and persistence of inhibitory Tregs in the tumor microenvironment and potentially by mitigating CD4+ T helper cell exhaustion." (PMID 33995422, 2021). "The analysis of MC38 tumor-infiltrating CD4+ T cells revealed a decreased number of CD4+ T cells in tumors from Cdk6fl/fl CD4-Cre mice." (PMID 34248938, 2021). "We observed increased GFP expression in tumor-infiltrating CD4+ and CD8+ T cells, as well as in macrophages and dendritic cells (DCs)." (PMID 34907171, 2021). "Treg cells act as a negative regulator of anti-tumor immunity by inhibiting the activation and differentiation of CD4 and CD8 positive T cells." (PMID 34249685, 2021). "In contrast, the expression of the ligand CD200 was higher in CD4+ T cells in the tumor than in CD4+ T cells from a normal lung (LFC = 3.9, p.adj = 0.0009)." (PMID 33918618, 2021). "We found higher percentages of CD4+ cells within the tumor (percentage of combined tumor parenchymal and stromal cells) in response to LFPRLR SMO treatment." (PMID 34375938, 2021). "For example, CD4+ naive T cells (cluster 0/cluster 2) located at the core of the tumor expressed more immune checkpoint molecules, such as CTLA4, LAG3, HAVCR2, and TNFRSF9/CD137." (PMID 34513820, 2021). "We further highlight the emerging observation that CD4+ T cell responses against tumours tend to be against self-derived epitopes." (PMID 32457487, 2021). "Next, we looked at the top dysregulated ligand/receptor pairs in tumor infiltrating CD4+ T cells and tumor." (PMID 34012510, 2021). "By using a mouse model with breast cancer, Lishay Parhi and colleagues found that the Fusobacterium nucleatum specifically accumulated inside the tumors and reduced tumor-infiltrating CD4+ and CD8+ T cells." (PMID 34656142, 2021). "In long-term, central memory and effector memory CD4/8 T cells were remarkedly expanded 9–25 folds in tumor-free mice after NPS treatment in comparison to tumor-bearing animals." (PMID 34887493, 2021). "Upon progression to the malignant phase, nascent tumor cells are primarily under control of CD4 and CD8 T cells." (PMID 34209393, 2021). "The infiltration levels of Th17 cells, Tfh cells, NKT cells, monocytes, neutrophils and CD4+ T cells in tumor tissues were lower than those in normal tissues." (PMID 34876062, 2021). "CD4+ T cells can influence cancer pathogenesis in various ways, either directly through cytolytic mechanisms or indirectly by modulating the tumor immune microenvironment." (PMID 33504936, 2021). "More recently, it has become clear that CD4+ T cells also have the ability to kill tumor cells directly and to coordinate the antitumor function of innate immune cells such as macrophages." (PMID 33546283, 2021). "Chronic stress increases the numbers of CD25+ cells within tumours while decreasing the numbers of CD4+ and CD8+ cells around tumours." (PMID 34988010, 2021). "We have shown that an anti‐hTAPBPL mAb significantly inhibits tumor growth in vivo, with a concomitant increase in tumor‐infiltrating CD4+ and CD8+ T cells and a decrease in the percentage of Tregs." (PMID 33938620, 2021). "The exact mechanisms and the role of CD4+ T cells and Treg cells in tumor immunotherapy warrant future studies." (PMID 33553191, 2021). "Tregs can inhibit TCR-mediated activation and proliferation of CD4+/CD8+T cells to promote tumor immune evasion." (PMID 35003090, 2021). "Our results suggest that the presence of tumor-infiltrating CD4+ cells provides protection to patients, and that CD8+ cells have a significant impact on the patient’s overall survival (OS) and progression-free survival (PFS)." (PMID 34885185, 2021). "In a murine tumor model, IL-2 secreted from tumor-resident CD4+ T cells increased CD8+ T cell proliferation and granzyme B expression." (PMID 34012451, 2021).
tumor (continued). "A significant negative correlation was observed between the geomean of CD25 expressed by CD4+ T cells and TLS-B cell density in the corresponding tumor sample, and to a lesser extent, between the percentage of CD25bright CD4+ T cells and TLS-B cell density." (PMID 33763071, 2021). "This study highlights the clinical relevance of CD4post in ACT and provides insights regarding the immunological nature of anti-CD4 treatment, which enhances anti-tumor response of CD8+ T cells." (PMID 34493727, 2021). "Overall, even if the origin of the cytotoxic CD4 T cells is still unclear, these findings highlight the importance of these cells in the direct killing of tumor cells." (PMID 34064410, 2021). "PD-1 expressing Foxp3+CD4+ regulatory T cells in the tumor can block the function of effector T cells, and therefore, it was important to define the effects of regulatory T cells on tumor growth and immunity." (PMID 34912335, 2021). "Tumour-infiltrating effector CD4+ T cells increased in combination-treated mice, compared to both isotype-treated and radiation-treated mice." (PMID 34784792, 2021). "In humanized NOG mice, both Cont-VV and its parental virus caused tumor clearance; however, only the armed-vector-injected tumor saw infiltration of CD4+, CD8+, and NK cells." (PMID 34445759, 2021). "As for tumor immune infiltration, NOP2 was significantly associated with CD4 + T cells, B cells, neutrophil cells, CD8 + T cells and dendritic cells infiltration." (PMID 34334108, 2021). "B cells can also promote anti-tumor immunity through providing Ags to both CD4+ and CD8+ T cells or through cross-presentation of Ags to other APCs." (PMID 34206956, 2021). "Confocal images showed a significant increase in host CD11c-positive DCs infiltrated in the tumor from AAA-CD4+ T cell-treated mice compared to that in PBS control mice and auto-CD4+ T cell-treated mice." (PMID 34625113, 2021). "In contrast, we found that naive B-cells, CD4 memory resting T-cells, gamma delta T-cells, activated NK cells, and mast cells showed high abundance in normal tissues, but low abundance in tumor tissues." (PMID 34763648, 2021). "Here, we undertook the analysis of tumor-infiltrating CD4 T cell exhaustion in patients with cancer and present data positioning exhausted CD4 T cells as players of response to ICB." (PMID 33332284, 2021). "In the context of cancer therapy, long-lasting response to tumor antigen is critical, hence the importance of developing immunotherapies that stimulate these responses via CD4+ TM cells." (PMID 34012451, 2021). "Among the different cell types, LILB4 expression is most correlated with tumor-infiltrating macrophages and CD4+ T cells." (PMID 33974041, 2021). "Although CD4+ T cells did not express OX40 in a significant level in A20 tumor, global CD4+ T-cell depletion impacts tumor growth through multiple mechanisms." (PMID 34907171, 2021). "This suggests that the host CD4+ T cells also play critical roles in the induction of anti-tumor immunity by AAA-CD4+ T-cell therapy." (PMID 34625113, 2021). "Transcriptome analysis of all lymphoid clusters indicated CD8 T cells as the main lymphocyte subset infiltrating the tumor upon combination therapy, with concomitant reduction of NK, CD4, and Treg clusters relative to PBS-treated tumors." (PMID 34446712, 2021). "The results indicate that COL1A1 expression has correlations with tumor purity and significant correlations with CD4+ T cells, Macrophage, Neutrophil and Dendritic cell in LUAD and LUSC." (PMID 33850663, 2021). "There was a significant increase in the number of CD4+ T cells and Foxp3 expressing cells in the lungs of this mouse that rejected the tumor." (PMID 34142056, 2021). "Blockade of LAIR-1 has also been shown to increase the number of tumor-infiltrating CD4+ and CD8+ T cells and enhance the efficacy of anti-PD-L1 treatment in humanized murine xenograft models of several cancers, including colon- and pancreatic cancer." (PMID 34956223, 2021).
tumor (continued). "T regs CD4 + FOXP3 + allow the progression of the tumor by expressing inhibitory factors that inhibit the anti-tumor TH1 response." (PMID 34952631, 2021). "In vivo therapeutic studies were performed in CT26 bearing mice where the therapeutic outcomes were expressed as tumor volume, expression of CD4 and CD8 as well as in vivo silencing." (PMID 34522209, 2021). "Amongst these, cDC2s, crucial for the activation of CD4+ T-helper cells in tumor-dLNs, were found to be increased in tumor-dLNs and tumors of KK and KV-vaccinated mice compared to untreated controls." (PMID 34885215, 2021). "We chose to use a dual checkpoint blockade regimen given our observation that 90Y-NM600 treatment increased CTLA-4 expression on CD4+ T cells and PD-L1 expression on tumor cells." (PMID 33995649, 2021). "TIMER website is a comprehensive resource which allow us to explore the correlation between six major tumor-infiltrating immune subsets (B cells, CD4 + T cells, CD8 + T cells, Neutrophils, Macrophages, and Dendritic cells) and gene expression." (PMID 34276760, 2021). "For example, scRNA-seq analyses were performed on the immune tumour microenvironment in colorectal cancer patients, providing evidence of the importance of Bhlhe40+ Th1-like CD4+ T cells in anti-tumour immunity and immunotherapy." (PMID 34621670, 2021). "Considering the cytotoxic effect of CD8+ T cells and regulation function of CD4+ T cells and Tregs in tumor immunity, chemokines closely related to the three TIL subtypes can reflect tumor immune environment to some degree." (PMID 35087741, 2021). "RT-qPCR examination of these tumor areas revealed a positive correlation between tumor burden and several immune genes found in ilea from pCC patients, such as Cd4, Bcl6, and Gata3." (PMID 33262469, 2021). "Firstly, we explored the relationship between β-catenin protein and tumor-immune infiltrating cells, including CD4+ T cells, neutrophils, CD8+ T cells, macrophages, dendritic cells, and B cells." (PMID 34764821, 2021). "Human tumor-derived exosomes were shown to inhibit IL-2 mediated proliferation of CD4 and CD8 T cells." (PMID 34831378, 2021). "Through secreting cytokines and attracting inflammatory cells to tumor cells, such as macrophages, neutrophils and NK cells, CD4+ T cells played an essential role in orchestrating the immune responses to cancers." (PMID 34844602, 2021). "After binging to cells APCs presenting at tumor cells, the body activates immune response, by activin CD4 T helper cells, CD8 cytotoxic T, and to eliminate or apoptosis of tumor cells." (PMID 33633793, 2021). "By modulating CD4+ T cells polarization and recruitment at tumor site, epigenetic therapies induce a favorable immune context in the TME that improve the response to ICI." (PMID 34262562, 2021). "Given that Th1 cells (CD4+ IFNγ+) play a key role in activating CD8+ T cells, we also analyzed the tumor-infiltrating CD4+ T cells." (PMID 34439144, 2021). "Compared with adjacent normal lung tissues, an increased proportion of CD45+ hematopoietic-derived cells, CD4+ T cell subtypes, Tregs and B cells was observed in tumor samples with a reduced frequency of myeloid cell populations." (PMID 33747957, 2021). "The mechanism of this phenomenon is still unrecognized, although in mouse models lacking CD4+ or CD8+ T cells the anti-CTLA-4 and anti-PD-1 treatment promoted normalization of tumor vessels via Th1 CD4+ helper T cell activation." (PMID 34439305, 2021). "CD4+ CD25− T cells can be converted into CD4+ CD25high FoxP3+ Tregs after coculture with tumor-derived exosomes." (PMID 34616851, 2021). "In advanced tumor samples (Cht and Cht+I2), both software programs concur with an increasing of CD4 T and B cells global relative percentage." (PMID 34680134, 2021). "Depletion of CD4+ T cells in VavP-Bcl2/CTSS chimera models confirm that CTSS is essential to support the communication and co-stimulatory signals between tumor B cells and CD4+ cells in the GC context." (PMID 34335584, 2021).